RFX1 (regulatory factor X1)
Description:
Regulatory factor essential for MHC class II genes expression. Binds to the X boxes of MHC class II genes. Also binds to an inverted repeat (ENH1) required for hepatitis B virus genes expression and to the most upstream element (alpha) of the RPL30 promoter.
Synonyms: EF-C; RFX; EFC
Tractability: PROTAC: ubiquitination databases record sites on it; its protein half-life has been measured.
Gene: Protein-coding gene on chromosome 19 (13,961,529 to 14,007,084, reverse strand). Ensembl gene ENSG00000132005.
Subcellular location: Nucleus
Subcellular location (Human Protein Atlas): Nucleoplasm; Vesicles
Gene Ontology:
Molecular function: protein binding; sequence-specific double-stranded DNA binding; DNA-binding transcription factor activity, RNA polymerase II-specific; RNA polymerase II cis-regulatory region sequence-specific DNA binding; DNA binding; DNA-binding transcription factor activity
Biological process: immune response; regulation of transcription by RNA polymerase II; regulation of DNA-templated transcription
Cellular component: nucleoplasm; chromatin; nucleus
Genetic constraint (gnomAD): Loss-of-function variants: 37 observed, 82.89 expected, observed/expected ratio (o/e) 0.45, 90% interval 0.34 to 0.59. The upper end of that interval is the gene's LOEUF score, 0.59, which puts it in group 2 of 6, group 1 being the genes least tolerant of losing a copy. Missense variants: 1,096 observed, 1,171.3 expected, observed/expected ratio (o/e) 0.94, 90% interval 0.89 to 0.98. Synonymous variants: 620 observed, 538.42 expected, observed/expected ratio (o/e) 1.15, 90% interval 1.08 to 1.23.
Homologues: Orthologues: macaque RFX1 (99% identical), chimpanzee RFX1 (99% identical), dog RFX1 (96% identical), pig RFX1 (95% identical), rat Rfx1 (92% identical), mouse Rfx1 (91% identical), guinea pig RFX1 (88% identical), tropical clawed frog rfx1 (67% identical), zebrafish rfx1a (61% identical), zebrafish rfx1b (53% identical), Drosophila melanogaster Rfx (35% identical). Paralogues in human: RFX3 (44% identical), RFX2 (42% identical), RFX6 (21% identical), RFX4 (19% identical), RFX7 (16% identical), RFX5 (9% identical), RFX8 (9% identical).
Diseases named in the same sentence as RFX1 in open-access papers:
RFX1 is named in the same sentence as 73 diseases in open-access papers, as found by Europe PMC text mining. Sharing a sentence is not in itself a finding about the gene and the disease. The quoted sentences say what the papers report.
systemic lupus erythematosus (15 papers, 2010 to 2025). An autoimmune multi-organ disease typically associated with vasculopathy and autoantibody production. "Rfx1 deficiency in macrophages alleviated intestinal inflammation in mice with colitis and kidney damage in lupus-like mice." (PMID 37733446, 2023). "Collectively, Rfx1 deficiency promotes the development of lupus-like mice model and exacerbates renal damage." (PMID 29422534, 2018). "We next investigated the role of RFX1 deficiency in the macrophage of IMQ-induced lupus-like mice." (PMID 37733446, 2023). "Importantly, the more severe lupus-like kidney damage and deposition of IgG and C3 in kidney were observed in mice with Rfx1 deficiency." (PMID 29422534, 2018). "In addition, we also induced lupus-like mice model by intraperitoneal injection of pristane in Rfx1-deficient mice." (PMID 29422534, 2018). "Similar to coronary atherosclerosis, decreased RFX1 expression in CD4+ T cells from patients with systemic lupus erythematosus induces histone H3 acetylation and reduces DNA methylation and H3K9 trimethylation, leading to IL-17A overexpression." (PMID 41425715, 2025). "Here we explore the function of Regulatory factor X1 (RFX1) in macrophage polarization by constructing colitis and lupus-like mouse models." (PMID 37733446, 2023). "The in vitro and in vivo experiments showed that RFX1 increased M1 macrophage polarization and promoted the pathogenesis of colitis or lupus in mice." (PMID 37733446, 2023). "It has been reported that the expression of RFX1 is decreased in the CD4+ T cells of lupus patients." (PMID 31737059, 2019). "It has been reported that the expression of RFX1 was decreased in the CD4+ T cells of lupus patients." (PMID 30857550, 2019). "Besides in tumors, RFX1 is involved in its transcriptional mechanism in coronary atherosclerosis and systemic lupus erythematosus." (PMID 41425715, 2025). "Rfx1 KO mitigated the pathogenesis of imiquimod-induced (IMQ-induced) lupus-like mice." (PMID 37733446, 2023). "Here we show reduced expression of the transcription factor RFX1 in CD4+ T cells from patients with systemic lupus erythematosus, which leads to IL-17A overexpression through increased histone H3 acetylation and decreased DNA methylation and H3K9 tri-methylation." (PMID 29422534, 2018). "Another mechanism of RFX1 gene silencing was observed in the progression of systemic lupus erythematosus (SLE)." (PMID 33964962, 2021). "RFX1 downregulation causes CD11a, CD70 and IL17A overexpression by reducing DNA methylation and increasing H3 acetylation levels in the promoter region of CD11a, CD70 and IL17A in the CD4+ T cells of systemic lupus erythematosus (SLE) patients, which contributes to autoimmune responses." (PMID 31737059, 2019). "In systemic lupus erythematosus (SLE), regulatory factor X 1 (RFX1) was found to be able to recruit HDAC1 to the promoter region of CD70 and deacetylate the histone substrate, resulting in a more condense chromatin structure and a decrease in the expression level of CD70." (PMID 35585975, 2022). "In systemic lupus erythematosus (SLE), RFX1 downregulated IL17A, CD70, and CD11a expression by recruiting DNMT1, HDAC1, and SUV39H1 to alter epigenetic modifications in CD4+ T cells from patients with lupus." (PMID 30857550, 2019). "Rfx1 conditional deletion in mice exacerbates experimental autoimmune encephalomyelitis (EAE) and pristane-induced lupus-like mice models." (PMID 29422534, 2018). "Beyond that, regulatory factor X1 (RFX1) and the nuclear factor interleukin-3-regulated protein (NFIL3, also known as E4BP4) are also reported in our previous study in human lupus CD4+ T cells." (PMID 28785369, 2017). "In addition, CHIP was upregulated in systemic lupus erythematosus patients’ CD4+ T cells and resulted in the ubiquitination and degradation of regulatory factor X 1 (RFX1), a transcription factor that suppresses systemic lupus erythematosus." (PMID 34831344, 2021).
systemic lupus erythematosus (continued). "RFX1 downregulation caused CD11a, CD70, and IL17A overexpression by reducing DNA methylation and increasing H3 acetylation levels in the promoter region of CD11a, CD70, and IL17A in the CD4+ T cells of systemic lupus erythematosus (SLE) patients, which contributed to autoimmune responses." (PMID 30857550, 2019). "Here we demonstrated an important novel role for RFX1 in the regulation of the increased IL-17A expression in CD4+ T cells of patients with SLE, as well as in the differentiation of Th17 cells and the development of the IL-17-related autoimmune diseases EAE and lupus in mice." (PMID 29422534, 2018). "It has been shown that autoimmune responses in SLE may partly be explained by Regulatory factor X-box 1 (RFX1) downregulation, which results in histone H3 hyperacetylation at the promoter region of CD11a and CD70 genein CD4+ T cells of patients with systemic lupus erythematosus (SLE)." (PMID 27669210, 2016).
hepatocellular carcinoma (10 papers, 2014 to 2025). A malignant tumor that arises from hepatocytes. "A cohort study including 124 patients with large HCC and 71 patients with small hepatocellular carcinomas found that reduced RFX1 in hepatocellular carcinoma tissues predicted a poor prognosis, as well as a high risk of recurrence." (PMID 41425715, 2025). "In contrast, RFX1 was positively correlated with immunomodulators in hepatocellular carcinoma as well as prostate cancer." (PMID 41425715, 2025). "RFX1 acted a prognostic biomarker in hepatocellular carcinoma and low RFX1 was correlated with poor prognosis." (PMID 36045400, 2022). "SNHG17 can promote tumor-like behavior in hepatocellular carcinoma cells via miR-3180-3p/RFX1." (PMID 34782005, 2021). "In addition, RFX1 expression is lower in some types of cancer such as esophageal adenocarcinoma and hepatocellular carcinoma." (PMID 31737059, 2019). "A cohort study involving patients having small hepatocellular carcinoma (HCC) analyzed the use of RFX1 as a prognostic marker for this disease." (PMID 33964962, 2021). "In esophageal squamous and hepatocellular carcinomas, SNHG17 can promote EMT by targeting miR-338-3p/SOX4 and miR-3180-3p/regulatory factor X-box 1 (RFX1) axes, respectively." (PMID 36185210, 2022). "And it was verified by in vitro experiments that knockdown of RFX1 facilitated the decreased expression of E-calmodulin as well as the increased expression of waveform proteins, which promoted the EMT and invasion of hepatocellular carcinoma cells." (PMID 41425715, 2025).
glioblastoma (7 papers, 2015 to 2025). The most malignant astrocytic tumor (WHO grade IV). "As discussed, increased RFX1 expression was associated with CD44 down-regulation in glioblastoma." (PMID 33964962, 2021). "Also, overexpression of RFX1 using lentiviral transfection in the F98 glioblastoma cell line caused a marked reduction in cell proliferation." (PMID 33964962, 2021). "In glioblastoma, RFX1 was shown to negatively regulate the self-renewal capacity of glioma stem cells through direct FGF1 suppression, and to inhibit tumor invasiveness via downregulation of CD44." (PMID 41425715, 2025). "Recent studies have confirmed that RFX1 directly reduces CD44 expression and inhibits glioblastoma invasion, suggesting the importance of RFX1 in tumor physiology." (PMID 41425715, 2025). "Within the context of glioblastoma, RFX1 appears to exert a potential negative regulatory influence on the self-renewal capacity of glioblastoma stem cells." (PMID 41425715, 2025). "Our Western blotting studies have confirmed that these agents increase the RFX1 protein in human glioblastoma cells." (PMID 39636301, 2024). "We have shown that RFX1 is a suppressive transcription factor to inhibit the migration, proliferation and invasion of human glioblastoma cells." (PMID 39636301, 2024). "Overexpression of RFX1 in human glioblastoma cells increases apoptosis and reduces cell proliferation, migration and invasion in cell culture or xenograft models." (PMID 39636301, 2024). "Thiazolidinediones and WY‐14643 inhibit the survival, migration and invasion of glioblastoma cells via increasing RFX1 in these cells under cell culture and xenograft conditions." (PMID 39636301, 2024). "Our results provide additional evidence for RFX1 as a therapeutic target for human glioblastoma and suggest that pioglitazone, rosiglitazone and WY‐14643 inhibit cancer cell behaviour of human glioblastoma cells via upregulating RFX1." (PMID 39636301, 2024). "In summary, we have shown that a bioinformatics‐based approach has identified that thiazolidinediones and WY‐14643 can induce RFX1 expression, which is confirmed by assessing the protein expression of RFX1 in human glioblastoma cells." (PMID 39636301, 2024). "RFX1 also prevented the metastasis of multiple glioblastoma cell lines via down-regulating CD44 expression." (PMID 33964962, 2021). "RFX1 itself is a relevant tumor suppressor transcription factor in glioblastoma due to its negative regulation of CD44 expression." (PMID 33964962, 2021). "A similar study using glioblastoma cell lines proved that RFX1 overexpression led to decreased cell invasion, migration, and proliferation mediated by direct targeting of CD44." (PMID 33964962, 2021). "This study was designed to identify the existing medications that could increase RFX1 in human glioblastoma cells and to determine whether these medications could inhibit the cancer cell behaviours." (PMID 39636301, 2024). "Importantly, these agents inhibit the migration, proliferation, survival and invasion of human glioblastoma cells, providing additional evidence for the role of RFX1 in regulating the cancer cell behaviour of glioblastoma cells." (PMID 39636301, 2024). "However, we have shown that RFX1 can induce apoptosis and inhibit cell proliferation of glioblastoma cells via inhibiting CD44 and related signalling molecules." (PMID 39636301, 2024). "In human glioblastoma cells, RFX1 downregulates fibroblast growth factor 1 expression." (PMID 37781522, 2023). "Thus, this study is designed to determine whether pioglitazone, rosiglitazone and WY‐14643 can reduce cancer cell behaviour of human glioblastoma via increasing RFX1." (PMID 39636301, 2024). "Thus, increasing RFX1 expression may be an effective therapeutic approach for many different types of cancers, including human glioblastoma." (PMID 39636301, 2024). "We have shown that regulatory factor X1 (RFX1), a transcription factor, inhibits the proliferation, migration and invasion of human glioblastoma cells." (PMID 39636301, 2024).
glioblastoma (continued). "Additionally, RFX1 overexpression may reduce the proliferation and invasion of glioblastoma cells." (PMID 37781522, 2023). "Recently, a dysregulated network of triplet molecules, including RFX1, TP73-AS1 lncRNA, and miR-197, was perceived to indicate a poor prognosis, survival, and tumor progression in glioblastoma multiforme." (PMID 33964962, 2021). "In a study, overexpression of RFX1 reduced FGF-1B mRNA expression, and neurosphere formation resulted in the inhibition of self-renewal in glioblastoma stem cells." (PMID 33964962, 2021). "RFX1 directly downregulated CD44 expression, affecting the ability for proliferation, survival, and invasion in glioblastoma cells." (PMID 30857550, 2019). "However, the effects of thiazolidinediones on glioblastoma cells and the role of RFX1 in the pharmacological effects of thiazolidinediones are not known." (PMID 39636301, 2024).
breast carcinoma (4 papers, 2015 to 2025). "An interactome map omitting linker genes constructed from different breast cancer types identified RFX1 as a differentially expressed molecule interacting with HER2 in HER2 positive breast cancer tissues." (PMID 33964962, 2021). "Significant changes in the methylation pattern of RFX1 seventh intron were also observed in tissue samples of breast cancer patients compared to adjacent healthy tissues." (PMID 33964962, 2021). "Additionally, in breast cancer cells, RFX1 participates in the activation of the SHP1 promoter in response to serum stimulation, thereby attenuating cell proliferation through ERK pathway suppression." (PMID 41425715, 2025). "Finally, the altered levels of RFX1 have valuable prognostic value in breast cancer and esophageal adenocarcinoma." (PMID 33964962, 2021). "RFX1 is a key player in the suppression of IGF-1 mediated breast cancer cell proliferation." (PMID 33964962, 2021). "RFX1 also has a putative binding site at the human kinesin family member 3A (KIF3A) gene promoter, whose inhibition contributed to the suppression of an aggressive form of breast cancer." (PMID 33964962, 2021). "SHP1, with the help of RFX1, could inhibit IGF1-induced cell proliferation, thereby accentuating survival in breast cancer cell lines MCF-7 and ZR-75–1." (PMID 33964962, 2021). "In breast cancer cell lines MDA-MB-468 and MCF-7, the IL-6/STA3 pathway plays a crucial role in EMT by upregulating TGF-β, a multifactorial cytokine that is again a target of RFX1 and a downstream signaling molecule of CD44 in breast cancer cells." (PMID 33964962, 2021).
glioma (4 papers, 2011 to 2025). A benign or malignant brain and spinal cord tumor that arises from glial cells (astrocytes, oligodendrocytes, ependymal cells). "In a methylation pattern analysis of different subsets of glioma and normal brain tissues, RFX1 was hypermethylated in early-onset gliomas, secondary gliomas, astrocytic and oligodendroglial tumors." (PMID 33964962, 2021). "Rfx1 expression was found to be down-regulated in gliomas as a result of promoter methylation and the reintroduction of Rfx1 in transfected glioma cells resulted in decreased cell proliferation, suggesting that Rfx1 may play a role as a tumor suppressor in glioma tumorigenesis." (PMID 21935353, 2011).
autoimmune disease (3 papers, 2018 to 2023). A disorder resulting from loss of function or tissue destruction of an organ or multiple organs, arising from humoral or cellular immune responses of the individual to their own tissue constituents. "To explore the expression pattern of RFX1 in macrophages of autoimmune diseases, we analyzed the single-cell RNA-Seq data of skin lesions from patients with SLE (GSE179633)." (PMID 37733446, 2023). "Here the authors show that the transcription factor RFX1 limits Th17 differentiation and is protective against the pathogenesis of Th17-driven autoimmune diseases." (PMID 29422534, 2018). "EAE is a typical Th17-related autoimmune disease modeled in mice, and Rfx1 expression was decreased significantly in CD4+ T cells from EAE mice compared with wild type (WT) mice." (PMID 29422534, 2018). "Here we present evidence that RFX1 is a negative regulatory factor in Th17 differentiation and autoimmune diseases." (PMID 29422534, 2018). "RFX1 expression was increased in inflammatory and autoimmune diseases." (PMID 37733446, 2023). "Collectively, our findings identify a unique role for RFX1 in Th17-related autoimmune diseases." (PMID 29422534, 2018). "We identified a potential RFX1 inhibitor, adenosine diphosphate (ADP), providing a potential strategy for treating autoimmune diseases." (PMID 37733446, 2023). "The roles of RFX1 in macrophages and autoimmune disease have not been reported." (PMID 37733446, 2023). "Therefore, we hypothesized that abnormally elevated LPS in patients with inflammatory and autoimmune diseases reduced the concentration of ADP in macrophages, thereby activating the regulatory function of RFX1 and promoting the inflammatory response." (PMID 37733446, 2023). "In conclusion, we have provided evidence that RFX1 downregulation contributes to the increased IL-17A expression and Th17 cell differentiation in the CD4+ T cells of patients with SLE, as well as promotes the pathologic changes of autoimmune diseases including EAE and lupus-like mice models." (PMID 29422534, 2018).
Hyperglycemia (3 papers, 2017 to 2023). An increased concentration of glucose in the blood. "KMT5A associated with RFX1 to modulate ENO1, thus involved in hyperglycemia-mediated EndMT in glomeruli of DN." (PMID 34803485, 2021).
cholangiocarcinoma (2 papers, 2021 to 2025). A carcinoma that arises from the intrahepatic biliary tree (intrahepatic cholangiocarcinoma) or from the junction, or adjacent to the junction, of the right and left hepatic ducts (hilar cholangiocarcinoma). "By comprehensively analysing the expression profile of RFX1 in pan-cancer, we found that RFX1 has higher expression in digestive tract tumors, including colon, cholangiocarcinoma and gastric cancer, compared to normal paraneoplastic tissues." (PMID 41425715, 2025). "Our in silico analysis revealed that a total of six TFs (SP1, CREB1, MAX, FHL2, RFX1 and HIF1A) were upregulated in cholangiocarcinoma tissues." (PMID 34199886, 2021). "Moreover, expressions of six TF genes (SP1, CREB1, MAX, FHL2, RFX1, and HIF1A) was positively correlated with the expression of ITGA6 and ITGB1 in cholangiocarcinoma tissues." (PMID 34199886, 2021).